KCNQ1OT1 (KCNQ1 opposite strand/antisense transcript 1)
Diseases named in the same sentence as KCNQ1OT1 in open-access papers (continued):
Sharing a sentence is not in itself a finding about the gene and the disease.
lung cancer (11 papers, 2017 to 2022). A malignant neoplasm involving the lung. "A previous research revealed that KCNQ1OT1 was upregulated in early stage lung cancer and was associated with prognosis in LC patients by suppressing cell proliferation." (PMID 32377169, 2020). "Stratified analyses indicated alteration of the predictive value of lncRNA KCNQ1OT1 for OS in lung cancer (pooled HR=1.45, 95% CI: 0.61-3.45, P=0.4)." (PMID 33994860, 2021). "Recently, a high level of KCNQ1OT1 was detected in lung cancer, promoting proliferation and invasion as well as chemoresistance of lung cancer cells." (PMID 31915311, 2020). "In previous studies, KCNQ1OT1 indicated a better prognosis in lung cancer." (PMID 33029085, 2020). "Additionally, the KCNQ1 Opposite Strand/Antisense Transcript 1 (KCNQ1OT1) gene is a lncRNA, which has been reported to be highly expressed in colorectal and lung cancers." (PMID 32850327, 2020). "High KCNQ1OT1 expression is correlated with malignant phenotypes in lung cancer." (PMID 32850327, 2020). "It has been proved that KCNQ1OT1 can promote cell proliferation and autophagy and inhibit cell apoptosis by regulating mir‐204‐5p/ATG3 axis, which provides a promising target for non‐small cell lung cancer (NSCLC) treatment." (PMID 34850551, 2022). "The transfection of si-KCNQ1OT1 can effectively knock down the expression of KCNQ1OT1, increasing KCNQ1 levels and, thus, inhibiting the malignancy and chemoresistance of lung cancer cells to paclitaxel." (PMID 32850327, 2020). "The two studies also showed YTHDF2 could recognize m6A-modified sites of lncRNA KCNQ1OT1 or PVT1 and regulate their stability, but whether ALKBH5 regulates the stability of PVT1 via YTHDF2 in lung cancer cells remains to be examined further." (PMID 36376862, 2022).
prostate carcinoma (11 papers, 2020 to 2025). A carcinoma that arises from epithelial cells of the prostate gland. "LncRNA KCNQ1OT1 was also proved to promote cell progression of prostate cancer through targeting on miR-211-5p/CHI3L1 axis." (PMID 36471281, 2022). "As a miRNA sponge, lncRNA KCNQ1OT1 can promote immune evasion by upregulating PD-L1 expression in prostate cancer and regulating immune escape in sorafenib-resistant hepatoma carcinoma cell cells 40,41." (PMID 33994860, 2021). "KCNQ1OT1 expression was positively associated with Chitinase 3 Like 1 (CHI3L1) expression and significantly promotes prostate cancer (PCa) cell proliferation, invasion, and metastasis." (PMID 34827600, 2021). "For instance, lncRNA KCNQ1OT1 promoted the progression of prostate cancer by suppressing CD8+ T cells cytotoxicity through the KCNQ1OT1/miR-15a/PD-L1 axis." (PMID 35059320, 2021). "We focused on the KCNQ1OT1/miR-15a/PD-L1 axis and explored its significance in regulating immune evasion and malignant behaviors of prostate cancer (PC) cells." (PMID 32821247, 2020). "In addition, numerous lncRNAs have been reported to regulate the sensitivity of cancer cells to the cytotoxicity of tumor-reactive T cells, such as SNHG4 or MALAT1 in diffuse large B cell lymphoma, and KCNQ1OT1 in prostate cancer." (PMID 36482354, 2022). "For example, LncRNA KCNQ1OT1 inhibits the cytotoxicity of CD8+ T cells and promotes the malignant ability of prostate cancer cells by targeting miR-15a/PD-L1 axis." (PMID 33665192, 2021).
gastric cancer (9 papers, 2009 to 2022). A primary or metastatic malignant neoplasm involving the stomach. "The SNPs of KCNQ1OT1 rs7128926 and rs7939976 have been shown to independently predict the recurrence-free survival and overall survival of gastric cancer patients." (PMID 34199840, 2021). "Finally, we expect to further validate the role of KCNQ1OT1/miR-378a-3p/RBMS1 axis in gastric cancer in the next study owing to the current experimental constraints." (PMID 35910231, 2022). "However, there are still no studies on how the KCNQ1OT1, miR-378a-3p, and RBMS1 axis play a role in the development and progression of gastric cancer." (PMID 35910231, 2022).
melanoma (9 papers, 2020 to 2025). A malignant, usually aggressive tumor composed of atypical, neoplastic melanocytes. "Using the real datasets obtained from melanoma patients, we showed that Cyclum can accurately infer the cell-cycle expression components, nominate novel cell-cycle genes (e.g., KCNQ1OT1 and FBLIM1), and elucidate latent associations between cell subpopulations and drug resistance." (PMID 32188848, 2020). "In melanoma cells, there is an elevated expression of KCNQ1OT1, which affects the miR-34a/STAT3 pathway, leading to the enhancement of expansion, migration, and aggression capabilities." (PMID 38462628, 2024). "KCNQ1OT1 promotes cell proliferation and metastasis in melanoma by sponging miR-153, which results in the upregulation of MET oncogene." (PMID 34638331, 2021). "KCNQ1OT1 is aberrantly upregulated in melanoma and retinoblastoma (RB) patient tissues compared with adjacent normal tissues." (PMID 34827600, 2021). "Furthermore, recent studies have shown that KCNQ1OT1 facilitates melanoma immune evasion through the miR-34a/STAT3/PD-L1 axis, indicating that KCNQ1OT1 is a potential immunotherapy target." (PMID 41502505, 2025). "Overexpression of KCNQ1OT1 contributed to the proliferation, migration, and invasion of melanoma and RB cells by sponging miR-153, and increasing MET proto-oncogene receptor tyrosine kinase (MET) and hypoxia-inducible factor-1α (HIF-1α) expression, respectively." (PMID 34827600, 2021). "KCNQ1OT1 (KCNQ1 overlapping transcript 1) expression is upregulated in melanoma tissues and cells." (PMID 34638331, 2021). "Current studies have shown that the metastasis of melanoma is related to the expression of certain genes and the activation of certain pathways, such as ABCB5 expression, lncRNA KCNQ1OT1, the MMP-9 signaling pathway, and the HGF-MET signaling pathway." (PMID 34582363, 2021). "Likewise, KCNQ1OT1 hinders the function of CD8 + T cells through the miR-34a/STAT3/PD-L1 axis, thereby facilitating immune evasion by melanoma cells." (PMID 38462628, 2024).
ovarian carcinoma (9 papers, 2020 to 2025). A malignant neoplasm originating from the surface ovarian epithelium. "Specifically, KCNQ1OT1 can recruit DNA methyltransferase to influence the progression of ovarian cancer cells." (PMID 41463281, 2025). "KCNQ1OT1 upregulation in ovarian cancer contributes to the enhancement of proliferation and migration of ovarian cancer cells by sponging miR-142-5p." (PMID 39039611, 2024). "Our findings evidenced that lncRNA KCNQ1OT1 aggravated ovarian cancer metastasis by decreasing EIF2B5 expression level, and provided a novel therapeutic strategy for OC." (PMID 36100884, 2022). "Interestingly, a study investigating the involvement of KCNQ1OT1 in ovarian cancer demonstrated an important feature of this lncRNA." (PMID 41463281, 2025). "Most notably, KCNQ1OT1 could facilitate proliferation/migration of ovarian cancer cells by up-regulating β-catenin." (PMID 34704918, 2021). "Two reports highlight the role of KCNQ1OT1 in ovarian cancer." (PMID 34204094, 2021). "This study indicates that KCNQ1OT1 stimulates ovarian cancer by modulating the miR-212-3p/LCN2 axis, thus it may be a potential therapeutic target." (PMID 34204094, 2021).
atherosclerosis (8 papers, 2020 to 2024). A disease characterized by the build-up of fatty material and calcium deposition in the arterial wall resulting in partial or complete occlusion of the arterial lumen. "Recently, other biological functions of KCNQ1OT1 have been reported, including those associated with fibrosis, cerebral ischemia, stroke atherosclerosis, oncogenesis, osteogenic differentiation, fracture healing, and cardiac hypertrophy." (PMID 35163809, 2022). "In other diseases, such as atherosclerosis, high levels of KCNQ1OT1 prevented cholesterol efflux and induced lipid accumulation in THP-1 macrophages." (PMID 38057885, 2023). "In contrast, KCNQ1OT1 silencing protected against atherosclerosis in apoE-/-mice and inhibited the lipid accumulation in THP-1 macrophages." (PMID 38057885, 2023). "Collectively, these in vivo results indicate that kcnq1ot1 functions as an important contributor to atherosclerosis." (PMID 33293505, 2020). "In summary, the present study has demonstrated an important role of kcnq1ot1 in facilitating atherosclerosis development and revealed a novel mechanism for ABCA1 regulation." (PMID 33293505, 2020). "Experimental data show that miR-183-3p may regulate the proliferation of vascular smooth muscle cells binding to KCNQ1OT1, a long-coding RNA, up-regulated in atherosclerosis." (PMID 39337512, 2024). "Evidence also showed that the rising level of KCNQ1OT1 repressed cholesterol excretion and exacerbated lipid deposition in macrophages, which could facilitate the formation of atherosclerosis." (PMID 36278219, 2022). "KCNQ1OT1 promoted atherosclerosis development by modulating miR-452-3p/HDAC3/ABCA1 pathway." (PMID 36100884, 2022). "Moreover, KCNQ1OT1 could aggravate atherosclerosis via regulation of lipid metabolism." (PMID 36278219, 2022). "Given the complexity of lncRNA action mechanisms, it is possible that kcnq1ot1 regulates ABCA1 expression and affect atherosclerosis progression by other pathways." (PMID 33293505, 2020).
myocardial ischemia (8 papers, 2018 to 2025). A disorder of cardiac function caused by insufficient blood flow to the muscle tissue of the heart. "Recent studies have demonstrated that kcnq1ot1 plays an important causative role in cardiovascular disease, such as cardiomyopathy and myocardial ischemia/reperfusion injury." (PMID 33293505, 2020). "lncRNA KCNQ1OT1 is overexpressed in mesenchymal stem cells, and lncRNA KCNQ1OT1 is protective against myocardial ischemia/reperfusion injury." (PMID 38836038, 2024). "LncRNA Kcnq1ot1 has been shown to be closely related to a variety of diseases, including long QT syndrome, cataracts, cancers, and myocardial ischemia/reperfusion injury." (PMID 30250027, 2018).
diabetic cardiomyopathy (7 papers, 2020 to 2023). Diabetic cardiomyopathy is a disorder of the heart muscle in people with diabetes. "For example, lncRNA Kcnq1ot1 regulates pyroptosis, in turn activating fibrosis, in diabetic cardiomyopathy." (PMID 37156816, 2023). "LncRNA KCNQ1 opposite strand/antisense transcript 1 (KCNQ1OT1) has been reported to involve in diabetic cardiomyopathy development." (PMID 32905431, 2020). "Moreover, KCNQ1OT1 aggravated fibrosis and pyroptosis in diabetic cardiomyopathy by targeting the miR-214-3p/caspase-1/TGF-β1/smad pathway." (PMID 36278219, 2022). "For instance, silencing lncRNA KCNQ1OT1 could alleviate pyroptosis and fibrosis in diabetic cardiomyopathy." (PMID 35443864, 2022). "Additionally, KCNQ1OT1 was reported to be upregulated in diabetic and KCNQ1OT1 knockdown inhibited pyroptosis in diabetic cardiomyopathy." (PMID 34654473, 2021). "In addition, KCNQ1OT1 was overexpressed in diabetic and induced pyroptosis in diabetic cardiomyopathy." (PMID 32905431, 2020).
acute myeloid leukemia (6 papers, 2020 to 2022). Acute myeloid leukemia (AML) is a group of neoplasms arising from precursor cells committed to the myeloid cell-line differentiation. "KCNQ1OT1 facilitates the progression of acute myeloid leukemia, as shown by increased proliferation, migration, and invasion of acute myeloid leukemia cells." (PMID 35498136, 2022). "LncRNA KCNQ1OT1 sponges miR-326 to control cell proliferation and differentiation in acute myeloid leukemia." (PMID 32297639, 2020). "Moreover, KCNQ1OT1 restrained apoptosis and contributed to cell proliferation in acute myeloid leukemia." (PMID 32905431, 2020).
ischemic stroke (6 papers, 2019 to 2024). A stroke disorder caused by obstruction of blood flow to the brain, due to thrombotic (local blood clot formation) or embolic (due to a blood clot or other material traveling from another site) event. "In conclusion, patients with upregulated KCNQ1OT1 expression were at a high risk of further ischemic stroke after TIA." (PMID 36278219, 2022). "Previous studies have shown that lncRNA KCNQ1OT1 is associated with risk factors for ischemic stroke, such as diabetes and myocardial infarction." (PMID 33029125, 2020). "Such a lncRNA, lncRNA KCNQ1OT1 has been implicated in many types of human diseases; specifically, KCNQ1OT1 was significantly upregulated in ischemic stroke, and its knockdown reduces infarct volume and neurological impairments in transient middle cerebral artery occlusion (tMCAO) mice." (PMID 35498136, 2022). "KCNQ1OT1 also mediates ischemic stroke-induced cellular damage by acting as a sponge for miR-153-3p, which leads to the upregulation of Forkhead box O3a (Foxo3)." (PMID 39021183, 2024). "They indicated that KCNQ1OT1 expression was elevated in ischemic stroke, while its knockdown lessened brain injury and suppressed autophagy in a mice model of ischemic stroke." (PMID 39021183, 2024). "Nevertheless, little has been known about the effects of KCNQ1OT1 on subsequent ischemic stroke after TIA." (PMID 36278219, 2022). "lncRNA KCNQ1OT1 is significantly upregulated in the peripheral blood of patients with ischemic stroke." (PMID 33029125, 2020). "In this study, we revealed that potassium voltage‐gated channel subfamily Q member 1 opposite strand 1 (KCNQ1OT1) was significantly upregulated in ischemic stroke." (PMID 30945454, 2019). "To explore the potential influence of KCNQ1OT1 on the development of ischemic stroke, we recorded neurological deficit scores at 1, 3, 7, and 14 days after tMCAO." (PMID 30945454, 2019). "Regarding ischemic stroke, there is evidence that lncRNA KCNQ1OT1 promotes neuronal injury." (PMID 39021183, 2024). "Since early inflammatory response reflected by hs-CRP was proven to play pivotal roles in ischemic stroke following TIA, we wondered whether there was any association between the expression of KCNQ1OT1 and hs-CRP in plasma." (PMID 36278219, 2022). "Fewer patients would survive from further ischemic stroke with their KCNQ1OT1 level over 1.29." (PMID 36278219, 2022). "Expression of KCNQ1OT1 > 1.29 predicts further ischemic stroke." (PMID 36278219, 2022). "To determine whether KCNQ1OT1 was related to ischemic stroke, we tested relative expression in AIS patients using Quantitative real‐time PCR (qRT‐PCR)." (PMID 30945454, 2019). "Additionally, KCNQ1OT1 could be regarded as an independent predictor for subsequent ischemic stroke." (PMID 36278219, 2022). "Thus, we hypothesized that KCNQ1OT1 might be dysregulated and exert crucial functions in ischemic stroke." (PMID 30945454, 2019). "However, the expression and function of KCNQ1OT1 in ischemic stroke are still unknown." (PMID 30945454, 2019). "In this study, we confirmed for the first time that KCNQ1OT1 is highly expressed in AIS patient plasma and can be used to indicate the severity of ischemic stroke." (PMID 30945454, 2019). "To determine the role of KCNQ1OT1 after TIA, we studied peripheral plasma samples from 231 individuals, including 166 patients without further neurological dysfunction after TIA and 65 patients who suffered subsequent ischemic stroke." (PMID 36278219, 2022). "Thus, we speculated that KCNQ1OT1, SND1-IT1, NAPA-AS1, and LINC01001 may interact with miR-24-3p and facilitate the regulation of LPAR3 and ADORA1 in ischemic stroke." (PMID 34483854, 2021).
Stroke (6 papers, 2019 to 2026). Sudden impairment of blood flow to a part of the brain due to occlusion or rupture of an artery to the brain. "According to the optimal diagnostic point, the expression level of KCNQ1OT1 over 1.29 was determined as an independent predictor for subsequent stroke events (p < 0.05, OR 6.142, and 95% CI 2.723–13.857)." (PMID 36278219, 2022). "In this study, we proposed that the expression of KCNQ1OT1 was upregulated in further ischemic events and positively associated with the stroke risk levels of TIA for the first time." (PMID 36278219, 2022). "For those who had subsequent stroke after TIA, the plasma KCNQ1OT1 level was increased strikingly in moderate/high-risk subgroups." (PMID 36278219, 2022). "It showed that the KCNQ1OT1 level was prominently upregulated in the subsequent stroke- positive group (p < 0.05)." (PMID 36278219, 2022). "In addition, the ABCD2 score elevated along with the increased expression of KCNQ1OT1 in TIA patients who suffered recurrent stroke (R2 = 0.2577, p < 0.05)." (PMID 36278219, 2022). "miR‐200 plays a neuroprotective role in stroke and is repressed by the upregulation of KCNQ1OT1." (PMID 35266286, 2022). "In addition, KCNQ1OT1 expression was positively correlated with stroke severity, which was evaluated based on National Institute of Health Stroke Scale (NIHSS) scores (R2 = 0.2170, p < 0.01)." (PMID 30945454, 2019). "Moreover, our study indicated that KCNQ1OT1 could be regarded as a predictive factor for subsequent stroke." (PMID 36278219, 2022). "Furthermore, KCNQ1OT1 was significantly increased in the plasma of patients with AIS, and its expression was positively correlated with the severity of stroke, which implied that KCNQ1OT1 may be a diagnostic biomarker or severity evaluation indicator." (PMID 33299883, 2020). "It is particularly noteworthy that LncRNA KCNQ1OT1, MALAT1, MIR17HG, and RMST are upregulated in hS3-treated healthy neuronal cultures, as these lncRNAs are known to be highly upregulated in stroke and inflammatory diseases." (PMID 41602576, 2026).
tongue squamous cell carcinoma (6 papers, 2019 to 2024). A squamous cell carcinoma that arises from the tongue. "Furthermore, the KCNQ1OT1 lncRNA is highly expressed in tongue squamous cell carcinoma and is associated with poor prognosis." (PMID 31065463, 2019). "Knockdown of KCNQ1OT1 in tongue squamous cell carcinoma inhibited the survival rate, proliferation, migration, invasion, and epithelial-mesenchymal transition of tongue squamous cell carcinoma cells." (PMID 39039611, 2024). "For example, high expression of the lncRNA KCNQ1OT1 was closely correlated with poor prognosis in tongue squamous cell carcinoma (TSCC) and promoted TSCC cell proliferation." (PMID 31417644, 2019). "In the same context, the imprinted lncRNA KCNQ1OT1 (LIT1) is dysregulated in human tumors, and seems to be related to chemoresistance in tongue squamous cell carcinoma and poor prognosis." (PMID 36866275, 2023).
type 2 diabetes (6 papers, 2012 to 2025). "KCNQ1 and KCNQ1OT1 are well-established risk genes for type 2 diabetes, and in our analysis, they exhibit the greatest variances in gene contribution score, underscoring their significant role in susceptibility to type 2 diabetes." (PMID 40163718, 2025). "Many studies have found that lncRNAs such as MALAT1, ANRIL/CDKN2BAS, HI-LNC25, and KCNQ1OT1 are closely associated with type 2 diabetes susceptibility genes, which might affect their expression." (PMID 34941711, 2021).
liver cancer (5 papers, 2020 to 2024). An epithelial or non-epithelial malignant neoplasm that arises from the liver. "Recent investigations have shown KCNQ1OT1/Kcnq1ot1 to be upregulated in various malignancies, including breast and liver cancers, promoting disease progression and metastasis." (PMID 39201613, 2024). "Similarly, the overexpression of KCNQ1OT1 promotes the occurrence and development of liver cancer." (PMID 32953888, 2020).